EIF5A (eukaryotic translation initiation factor 5A)
Diseases named in the same sentence as EIF5A in open-access papers (continued):
Sharing a sentence is not in itself a finding about the gene and the disease.
parasitemia (4 papers, 2012 to 2021). "Infected NMRI mice transfected with schizonts transgenic for plasmodial eIF-5A- or DHS-specific shRNA showed a 50% reduced parasitemia in comparison to the untransfected control within 2 to 9 days post infection." (PMID 22694849, 2012). "This PK-PD model allows for mathematical simulations, produces testable predictions, and has implications for the study of deferiprone and ciclopirox as inhibitors of eIF5A hydroxylation in other clinical conditions known to involve hypusine formation, such as cancer and parasitic diseases." (PMID 27191165, 2016). "Interestingly, mice infected with transgenic schizonts expressing either the eIF-5A or dhs shRNA showed an elevated parasitemia within the first two days post infection which then decreased intermittently." (PMID 22694849, 2012). "Interestingly, mice transfected with eIF‐5A or DHS shRNA expression plasmids showed elevated parasitemia during the first 2 days after inoculation of transfected schizonts, followed by an intermittent decrease in parasitemia before succumbing death due to high parasitemia." (PMID 27516964, 2016). "In vivo knockdown of eIF-5A and DHS by expression of shRNAs after infection in a rodent model decreased parasitemia intermittently in the development of cerebral malaria." (PMID 22694849, 2012). "After 9 days post infection, parasitemia increased significantly in both infection experiments, harbouring either the transgenic schizonts with the DHS-shRNA or the eIF-5A-shRNA." (PMID 22694849, 2012). "By contrast, the mock strain displayed a parasitemia of 9% at day 6 post infection, compared to the transfected parasites with the DHS-shRNA (4.5%) or the eIF-5A-shRNA." (PMID 22694849, 2012).
prostate carcinoma (4 papers, 2020 to 2025). A carcinoma that arises from epithelial cells of the prostate gland. "Recently, it has demonstrated that eIF5A is widely involved in the pathogenesis of many diseases, including upper urinary tract urothelial carcinoma and prostate cancer (PCa)." (PMID 32522053, 2020). "Elevated expression of eIF5A is associated with unfavorable prognosis in several cancers, but direct evidence for a role for eIF5A in prostate cancer is lacking." (PMID 37591798, 2023). "With siRNA screens, several of these were indicated in survival (DDX6, EIF4A3, PABPN1), growth (e.g., EIF5A, HNRNPH2, LRRC47, and NVL), and migration (e.g., NOL3 and SLTM) of prostate cancer cells." (PMID 37591798, 2023).
glioma (3 papers, 2012 to 2020). A benign or malignant brain and spinal cord tumor that arises from glial cells (astrocytes, oligodendrocytes, ependymal cells). "In order to establish an in vitro model for further functional characterisation of the hypusine modification in gliomas, we analysed the expression of eIF-5A, eIF-5A2, DHS and DOHH in different cell lines." (PMID 22927971, 2012). "Using immunohistochemistry (IHC), we found elevated expression levels of DHS, DOHH and eIF-5A in 173 glioma samples with different grades." (PMID 22927971, 2012). "To evaluate a possible role of eIF-5A and the hypusine synthesizing enzymes in glioma, we analysed samples from 173 glioma patients." (PMID 22927971, 2012). "Our findings reveal that FOXD1‐AS1, a miR339/342 target, affected biological processes via protein eIF5a; thus, it might be considered as a novel emerging oncogenic biomarker and a potential target against glioma." (PMID 31102349, 2020). "In conclusion, our results showed that FOXD1‐AS1, a miR339/342 target, might function as an oncogene to facilitate tumor cell proliferation and inhibited apoptosis via targeting protein eIF5a in glioma." (PMID 31102349, 2020). "This hypothesis is substantiated by the finding that in samples of two non-glioma patients, eIF-5A, eIF-5A2 and DHS expression was mainly detectable in persisting neurons, ependymal and some other brain tissues, but rarely or not at all in astrocytes." (PMID 22927971, 2012). "Interestingly, regulation of FOXD1‐AS1 in glioma cells did not significantly affect eIF5a mRNA expression." (PMID 31102349, 2020). "The result showed that eIF5a mRNA was not changed when the expression of FOXD1‐AS1 was adjusted in Hs683 and U251 glioma cell lines." (PMID 31102349, 2020).
neuroblastoma (3 papers, 2020 to 2022). Neuroblastoma (NB) is the most common solid, extracranial childhood tumor. "The spermidine and deoxyhypusine synthase (DHPS) inhibitor, GC7, inhibits activation of EIF5A and induces apoptosis of neuroblastoma cells via the regulation of the p21/Rb signaling axis." (PMID 33996900, 2021). "Given the pleiotropic functions of eIF5A and by extension the hypusination enzymes, this system is being considered as a target for a range of cancers including multiple myeloma, B-Cell lymphoma, and neuroblastoma." (PMID 36511302, 2022).
Stroke (3 papers, 2021 to 2022). Sudden impairment of blood flow to a part of the brain due to occlusion or rupture of an artery to the brain. "In this latter case, organ transplantation, myocardial infarction or stroke are concerned, and the current literature defines eIF5A as a new drug target with a high level of potential benefit for patients with these diseases or injuries." (PMID 34952646, 2021). "FoxO3 and eIF5A are just two recent examples of how data obtained from tolerant species can turn about into potential treatments for stroke, at the moment in the experimental setting only." (PMID 34681788, 2021). "Recently, inhibition of eIF5A hypusination pathway was tested as a potential target for stroke." (PMID 34681788, 2021). "All these recent results open up a new area of research in which targeting eIF5A could preserve cells from I/R either in pre-treatment for organ transplantation or in post-treatment following stroke." (PMID 34952646, 2021). "Among them, Foxo3 and Eif5A were reported to mediate anoxic survival in Drosophila and Caenorhabditis elegans, respectively, and those results were confirmed in experimental models of stroke." (PMID 34681788, 2021).
type 1 diabetes (3 papers, 2019 to 2022). "Overall, inhibition of eIF5a hypusination is suggested to be protective in mouse models of type 1 diabetes." (PMID 35296698, 2022).
astrocytoma (2 papers, 2012 to 2020). "Although eIF-5A, DHS and DOHH are highly conserved and likewise expressed in healthy tissues, their overexpression in aggressive astrocytomas and the enhanced responsiveness of GMB cells compared to normal astrocytes render these protein potential therapeutic targets in this intracranial neoplasm." (PMID 22927971, 2012).
dengue (2 papers, 2010 to 2016). "Upon dengue virus infection of C636 cells, eukaryotic initiation factor 5A (eIF5A) (mRNA and protein) is upregulated, and inhibition of eIF5A activity resulted in increased cell death in infected cells." (PMID 27460797, 2016). "Co-localization of eIF5A and dengue proteins was shown in certain areas of infected C6/36 cells." (PMID 20819232, 2010).
heart failure (2 papers, 2023 to 2025). Inability of the heart to pump blood at an adequate rate to meet tissue metabolic requirements. "For example, an antibiotic, ciclopirox, was repurposed to reduce cardiac fibrosis by inhibiting eIF5A activity in animal models of heart failure, following myocardial infarction." (PMID 40869184, 2025). "However, the mechanism of how eIF5A hypusination is increased in MI or heart failure remains unclear." (PMID 36826549, 2023).
iron deficiency (2 papers, 2012 to 2020). "Next, we determined if eIF5A regulation under iron deficiency was based on a transcriptional mechanism and attempted to identify the implicated factor." (PMID 33379337, 2020). "Eukaryotic translation initiation and elongation factors have been implemented in various cellular processes, including cell division, cell growth and cell death, as well as in plant response to iron deficiency; eIF5A served as a general, non-specific control." (PMID 22340370, 2012).
ischemia (2 papers, 2015 to 2021). A hypoperfusion of the BLOOD through an organ or tissue caused by a PATHOLOGIC CONSTRICTION or obstruction of its BLOOD VESSELS, or an absence of BLOOD CIRCULATION. "We have previously shown the high effectiveness of GC7 pretreatment, a specific and reversible eIF5A hypusination inhibitor, in protecting the kidney from ischemia situations and proximal convoluted tubule cells (PCT) from anoxia." (PMID 35008578, 2021). "Myocardial ischemia/reperfusion (but not ischemia alone) markedly increased the plasma levels of eIF5A, and treatment with anti-eIF5A neutralizing mAbs significantly reduced myocardial injury." (PMID 26348594, 2015). "No significant changes in the plasma eIF5A levels were observed between the control condition (before ischemia) and after 30 min of ischemia (immediately before reperfusion)." (PMID 26348594, 2015).
myocardial infarction (2 papers, 2021 to 2023). Gross necrosis of the myocardium, as a result of interruption of the blood supply to the area, as in coronary thrombosis. "In this study, we found that increased hypusinated eIF5A protein levels were associated with cardiac fibrosis and heart dysfunction in myocardial infarction (MI) mouse models." (PMID 36826549, 2023).
myocardial ischemia (2 papers, 2015 to 2017). A disorder of cardiac function caused by insufficient blood flow to the muscle tissue of the heart. "In vivo treatment with anti-eIF5A neutralizing mAbs significantly reduced myocardial ischemia/reperfusion injury." (PMID 29057797, 2017). "We developed a sandwich enzyme-linked immunosorbent assay (ELISA) using YSPN2-74-18 and YSP5-45-36 and measured the plasma levels of eIF5A in rats that were subjected to myocardial ischemia/reperfusion." (PMID 26348594, 2015). "In contrast, myocardial ischemia (30 min)/reperfusion (15 and 30 min) clearly increased eIF5A expression on the plasma membrane of many cardiac myocytes." (PMID 26348594, 2015). "Next, we analyzed the effects of N1-guanyl-1,7-diaminoheptane (GC7), a hypusination inhibitor that blocks deoxyhypusine synthase (DHS) function, and the anti-eIF5A neutralizing mAbs in a rat model of myocardial ischemia/reperfusion." (PMID 26348594, 2015). "Myocardial ischemia/reperfusion (but not ischemia only) rapidly and markedly increased plasma levels of eIF5A, which returned to the control levels within 60 min." (PMID 29057797, 2017).
rectal cancer (2 papers, 2021 to 2024). A primary or metastatic malignant neoplasm that affects the rectum. "Consequently, EIF5A was designated as the key gene associated with radioresistance in rectal cancer." (PMID 39290702, 2024). "As anticipated, EIF5A exhibited upregulation in both colon and rectal cancer within the TCGAcohort, as confirmed by GEPIA analysis." (PMID 39290702, 2024).
toxoplasmosis (2 papers, 2021 to 2024). A parasitic disease contracted by the ingestion or fetal transmission of toxoplasma gondii. "Our results provide a potential source for understanding the role of eIF-5A during T. gondii pathogenesis, which will aid in controlling toxoplasmosis in the near future." (PMID 34039408, 2021). "Importantly, these findings provide insight into the biological function of eIF-5A during invasion and growth of T. gondii tachyzoites, which will lead to the development of an effective vaccine or drug target against toxoplasmosis." (PMID 34039408, 2021). "Therefore, recombinant protein vaccines or nanovaccines based on eIF-5A might be helpful in preventing and controlling toxoplasmosis, but further research is needed to verify this conclusion." (PMID 38276673, 2024).
ZIKV infection (2 papers, 2019 to 2022). "Hence, an unbiased assessment of translational changes induced by ZIKV infection reveals translational control of polyamine metabolism that is required for the unique hypusine modification of the eIF5A translation factor and has been implicated as a target for antiviral therapies." (PMID 35891396, 2022). "Moreover, other eukaryotic translation factors that were significantly up-regulated by ZIKV infection, although only ≈30%, include eIF4H and eIF5A-1." (PMID 30984137, 2019).
amebiasis (1 paper, 2021). A parasitic infectious disorder caused by amoebas. "Taken together, these results have underscored the essentiality of eIF5A and DHS, for proliferation and potentially in the differentiation of this parasite, and suggest that the hypusination associated pathway represents a novel rational target for drug development against amebiasis." (PMID 33592076, 2021).
amoebic dysentery (1 paper, 2021). "In the present study, we described the role of eIF5A, its posttranslational modifications (PTM), and the biosynthetic pathway needed for the PTM in Entamoeba histolytica, the protozoan parasite responsible for amoebic dysentery and liver abscess in humans." (PMID 33592076, 2021).
asthma (1 paper, 2026). "Additionally, we found that the association effect estimates of cold were significantly higher among participants with asthma compared with non-asthmatic participants for four proteins (AGRE2, CTSC, EIF5A, and NBN)." (PMID 41541696, 2026).
breast tumor (1 paper, 2025). "The DEG analysis showed that the EIF5A expression in CD4+ T cell was significantly downregulated in breast tumor cells versus normal cells (logFC = −0.21, p = 1.4 × 10−4), which is the same direction of effect as our MR findings." (PMID 41216857, 2025).
cardiac hypertrophy (1 paper, 2023). "As an eIF5A hypusination inhibitor, CPX reduces cardiac hypertrophy and fibrosis and improves cardiac functions in mouse preventive and reversal MI models." (PMID 36826549, 2023).
cerebral malaria (1 paper, 2012). A sequestration of Plasmodium falciparum in the brain, which can cause coma and/or seizures. "CNI-1493 prevented infected mice from experimental cerebral malaria by decreasing the levels in hypusinated eIF-5A and serum TNF, implicating a link between cytokine signaling and the hypusine pathway." (PMID 22694849, 2012).
COVID-19 (1 paper, 2025). A disease caused by infection with severe acute respiratory syndrome coronavirus 2. "Among these 16 protein-coding genes, the roles of BTN3A1, EIF5A, and NDUFA6 were previously identified in the pathogenesis of COVID-19, suggesting a potential link between their expression and the development of Long COVID." (PMID 41325417, 2025).
cyst (1 paper, 2021). A sac-like closed membranous structure that may be empty or contain fluid or amorphous material. "We have shown that Entamoeba eIF5A is involved in excystation, conversion from the cyst to the trophozoite, but not in encystation." (PMID 33592076, 2021).
Granuloma (1 paper, 2016). A compact, organized collection of mature mononuclear phagocytes, which may be but is not necessarily accompanied by accessory features such as necrosis. "In addition to its stimulatory role on TLR-mediated transcription, Mincle enhanced the translation of key genes required for nitric oxide synthesis through p38 and eIF5A hypusination, leading to granuloma resolution." (PMID 27089465, 2016).
Infertility (1 paper, 2026). "Conditional knockout of Eif5a (SKO) causes complete infertility in male mice due to round spermatid arrest." (PMID 41486816, 2026).
influenza (1 paper, 2025). An acute viral infection of the respiratory tract, occurring in isolated cases, in epidemics, or in pandemics; it is caused by serologically different strains of viruses (influenzaviruses) designated A, B, and C, has a 3-day incubation period, and usually lasts for 3 to 10 days. "Certain RNA viruses, including influenza, directly hypusinate eIF5a in stromal cells to prevent interferon production and thus promote viral replication." (PMID 40510183, 2025).
Insulin resistance (1 paper, 2013). Increased resistance towards insulin, that is, diminished effectiveness of insulin in reducing blood glucose levels. "Insulin resistance causes an environment in which deoxyhypusine synthase (DHS) promotes cytokine-induced inflammation in β-cells, as well as catalyzes the conversion of lysine to hypusine that is unique to the translational elongation factor eIF5A found in the endoplasmic reticulum (ER)." (PMID 24358323, 2013).
intestinal tumors (1 paper, 2020). "In contrast with these studies, our data show that inhibition of CRC cells does not modify ERK content and phosphorylation, thus supporting the conclusion that EIF5A function is not coupled to KRas expression and activity in intestinal tumors." (PMID 33303756, 2020).
intraepithelial neoplasia (1 paper, 2012). A precancerous neoplastic process that affects the squamous, glandular, or transitional cell epithelium without evidence of invasion. "Eukaryotic translation initiation factor 5A-1 (2-IF5A1) was upregulated by LR treatment (cluster F) and has been demonstrated to be a proliferation biomarker in vulvar high-grade intraepithelial neoplasia (VIN)." (PMID 23024692, 2012).
lymph node metastasis (1 paper, 2020). "Both isoforms of EIF5A have been investigated for their association with human cancer malignances, while EIF5A2 has been shown to be involved in tumor progression, poor prognosis, and lymph node metastasis." (PMID 32605067, 2020).
metastatic cancers (1 paper, 2020). A carcinoma which has spread from the original site of growth to another anatomic site. "The human eIF5A-1 isoform is abundant and implicated in some cancer types; the eIF5A-2 isoform is absent in most cells but becomes overexpressed in many metastatic cancers." (PMID 33379337, 2020).
muscular disease (1 paper, 2024). Myopathy is a peripheral nervous system disease consisting of any abnormal condition or disease of the muscular tissues; commonly designates a disorder involving skeletal muscle. "Our findings suggest that the spermidine-eIF5A axis represents a promising pharmacological target in efforts to activate endogenous SCs for the treatment of muscular disease." (PMID 39251577, 2024).
non-alcoholic steatohepatitis (1 paper, 2022). "Here the authors report that EIF5A hypusination, which regulates mitochondrial protein synthesis, is reduced during non-alcoholic steatohepatitis (NASH), which can be prevented by spermidine to inhibit the progression of NASH in mice." (PMID 36057633, 2022).